MIAT (myocardial infarction associated transcript)
Diseases named in the same sentence as MIAT in open-access papers (continued):
Sharing a sentence is not in itself a finding about the gene and the disease.
breast cancer (continued). "The 3-year survival rate of breast cancer patients was inversely correlated with the level of MIAT expression, and stage III patients expressed higher MIAT and lower DLG3 than Stage I-II." (PMID 37901333, 2023). "Knockdown of MIAT inhibited breast cancer cell proliferation, migration, invasion, and EMT and increased the rate of apoptosis in breast cancer cells." (PMID 34209776, 2021). "MIAT promotes the growth and metastasis of GC and colorectal cancer (CRC) cells via different pathways, and affects the response of breast cancer (BC) cells to estrogen." (PMID 33767996, 2021). "The data indicated an important role of the ER stress-mediated GRP78/OCT4/lncRNA MIAT/AKT pathway in cell resistance to 5-FU, highlighting potential molecular targets for combating 5-FU resistance in breast cancer." (PMID 32872257, 2020). "Our study also contributes to the existing evidence on MIAT and FAM83H‐AS1 as crucial lncRNA expressed at preliminary stages of breast cancer." (PMID 30959550, 2019). "Second, we have examined the effects of MIAT down-regulation on the short- and long-term survival of breast cancer cells and on the expression of OCT4, since OCT4 together with MIAT constitutes a regulatory loop in embryonic stem cells and malignant B cells." (PMID 29914974, 2018). "The present work also supports the existence of an MIAT and OCT4 axis involved in the regulation of breast cancer cell survival." (PMID 29914974, 2018). "To validated the results from TCGA, we detected MIAT mRNA level in the human normal breast epithelial cell line MCF-10A and breast cancer cell lines MCF-7, MDA-MB-231, MDA-MB-468, T-47D, SK-BR-3 and MDA-MB-453." (PMID 29100300, 2017). "Knockdown MIAT led to inhibit cell proliferation, migration, invasion and epithelial-mesenchymal transition (EMT) while promote apoptosis in breast cancer cells." (PMID 29100300, 2017). "To investigate the function of MIAT in breast cancer, we transfected MIAT-siRNA or scramble siRNA into MDA-MB-231 cells to knockdown MIAT." (PMID 29100300, 2017). "Furthermore, after conducting data mining in silico using public databases, the results of our study pointed to 4 lncRNAs, MIAT, KCNQ1OT1, LOC100270804, and FLJ10038, with good potential as candidate biomarkers for breast cancer." (PMID 34209776, 2021). "Unlike previous studies that showed an increased MIAT expression levels in the triple positive (ER, PR, and Her2 positive) tumor tissues, our results showed that MIAT expression was not changed in the triple positive breast cancer samples." (PMID 29914974, 2018). "There were positive correlation between MIAT and DUSP7 expression in breast cancer patients." (PMID 29100300, 2017). "There were positive correlation between MIAT and DUSP7 in breast cancer patients (R=0.226, P<0.05)." (PMID 29100300, 2017). "Also MIAT downregulation suppressed epithelial-mesenchymal transition (EMT) and decreased migration and invasion in MDA-MB-231 and MCF-7 breast cancer cell lines." (PMID 29100300, 2017). "Compared to normal controls, MIAT was down-regulated in luminal B breast cancer tumor tissues which were inconsistent with our results, while S100A7, CCL5 and WT1-AS were up-regulated in luminal B breast cancer tumor tissues which were consistent with our results." (PMID 31795964, 2019). "To further investigate whether the mRNA expression levels of MIAT exhibit changes in breast cancer, we utilized breast cancer cDNA arrays (BCRT101, BCRT102, and BCRT104) from OriGene Inc and determined MIAT expression levels in breast cancer and normal tissues." (PMID 29914974, 2018). "The expression of MIAT and DUSP7 were all negative or all positive in the consecutive sections of breast cancer TMA." (PMID 29100300, 2017).
cardiac hypertrophy (19 papers, 2017 to 2025). "The upregulation of MIAT was associated with the decrease in miR-93 in Ang II-induced cardiac hypertrophy in rat." (PMID 30305865, 2018). "In addition, lncRNA myocardial infarction associated transcript (MIAT) has been demonstrated to be a pro-hypertrophic regulator in cardiac hypertrophy induced by Ang II via acting as a molecular sponge for miR-150." (PMID 28287427, 2017). "For example, overexpression of MIAT exacerbates cardiac hypertrophy via the PPARα/CPT-1a signaling pathway." (PMID 40290189, 2025). "Contrary to effects observed in the H9c2 cells after the knockdown of MIAT, the overexpression of MIAT significantly increased the cardiac hypertrophy phenotype of AngII-treated cells." (PMID 35383152, 2022). "And in Ang II-induced mouse myocardial hypertrophy model and H9c2 cells, lncRNA MIAT overexpression can promote hypertrophy by sponging miR-150, and which upregulate in diabetic hearts and promote cardiac fibrosis." (PMID 35711309, 2022). "The results provided a new understanding of the MIAT and m6A RNA methylation reading protein, Ythdf2, function and mechanism in cardiac hypertrophy and highlighted the potential therapeutic benefits in the heart." (PMID 35383152, 2022). "RT-qPCR assay indicated that the promotive effect of AngII on cardiac hypertrophy phenotype was suppressed by MIAT knockdown." (PMID 35383152, 2022). "Perhaps the most remarkable finding of our research was the demonstration that MIAT plays an important regulatory role in cardiac hypertrophy through the m6A methylated reading protein Ythdf2 in vitro cellular model." (PMID 35383152, 2022). "We found that lncRNA MIAT mRNA level, and m6A RNA methylation reading protein Ythdf2 mRNA and protein levels, were significantly increased in the cardiac hypertrophy model both in vivo and vitro." (PMID 35383152, 2022). "A recent study elicited that MIAT is highly expressed in the angiotensin II-treated cardiomyocytes, and down-regulation of MIAT suppresses angiotensin II-induced cardiac hypertrophy by regulation of the miR-93/Toll-like receptor 4 axis." (PMID 33819189, 2021). "In response to AngII, MIAT acts as a molecular sponge of miR-93 which participates in the inactivation of the PI3K/Akt/mTOR pathway via targeting TLR4 in AngII-induced cardiac hypertrophy." (PMID 32754048, 2020). "Another study suggested that MIAT is significantly overexpressed in Ang II-induced cardiac hypertrophy in a mouse model and in H9c2 cells, which is in line with the results in our study." (PMID 31237148, 2019). "Accordingly, the study suggested that MIAT acts as sponge to inhibit miR-150 expression and enhanced cardiac hypertrophy." (PMID 30013975, 2018). "We found that MIAT and Ythdf2 were significantly increased during cardiac hypertrophy." (PMID 35383152, 2022). "MIAT or Ythdf2 overexpression aggravated cardiac hypertrophy, and vice versa." (PMID 35383152, 2022). "In our previous study, we demonstrated that downregulation of MIAT could inhibit the expression of cardiac hypertrophy indicators ANP and BNP in ISO-treated neonatal rat ventricular myocytes (NRVMs)." (PMID 35383152, 2022). "In this study, we demonstrated that MIAT influenced AngII-induced cardiac hypertrophy by regulating the expression of a key m6A RNA methylation enzyme, Ythdf2, and may influence its downstream target genes PPARα/CPT-1a." (PMID 35383152, 2022). "As anticipated, Ythdf2 functioned as a downstream of MIAT in cardiac hypertrophy." (PMID 35383152, 2022). "Finally, we found that MIAT was a necessary regulator of cardiac hypertrophy due to its regulation of the Ythdf2/PPARα/CPT-1a axis." (PMID 35383152, 2022). "To explore the mechanism of MIAT in cardiac hypertrophy, we first investigated whether MIAT and Ythdf2 actually interacted." (PMID 35383152, 2022).
cardiac hypertrophy (continued). "Additionally MIAT expression is upregulated in cardiomyocytes under AngII treatment, participating as an inducer of cardiac hypertrophy by activation of the PI3K/Akt/mTOR pathway via TLR4 upregulation by sponging miR-93 in cardiomyocytes." (PMID 32754048, 2020). "A previous study has suggested that MIAT is overexpressed in Ang II-induced cardiac hypertrophy, and the downregulation of MIAT is able to decrease Ang II-induced overexpression of hypertrophic markers, and also alleviate Ang II-induced hypertrophic phenotypes in cells." (PMID 31237148, 2019). "Furthermore, we discovered that Ythdf2 function was a downstream of MIAT in cardiac hypertrophy." (PMID 35383152, 2022). "In addition, lncRNA MIAT is significantly increased in Ang II-induced cardiac hypertrophy and contributes to the pathological development by suppressing miR-150 expression in cardiomyocytes; moreover, miR-150 is a downstream effector of MIAT in the development of cardiac hypertrophy." (PMID 33465375, 2021). "The result showed that the expression of lncRNAs were significantly different in cardiac hypertrophy model and control group by high-throughput microarray detection (GSE169580), among which lnc-MIAT was significantly increased." (PMID 35383152, 2022). "MIAT-mediated sponging of miR-93 led to upregulation of TLR4 and activation of hypertrophic PI3K/Akt/mTOR signaling, thereby leading to AngII-induced cardiac hypertrophy." (PMID 32241300, 2020). "In particular, MIAT knockdown can enhance miR-93 and inactivate the PI3K/Akt/mTOR pathway via regulating the TLR4 in angiotensin II-induced cardiac hypertrophy." (PMID 32605220, 2020). "In contrast, MIAT knockdown or miR-93 overexpression led to a significant inhibition on the protein levels of PI3K, p-AKT, and p-mTOR and blunted Ang II-mediated cardiac hypertrophy." (PMID 30305865, 2018). "Successful establishment of the cardiac hypertrophy model was confirmed by an obviously increased protein expression level of ANP, BNP, β-MHC and Ythdf2 in western blot and a clearly increased relative mRNA expression level of ANP, BNP, β-MHC, Ythdf2, and MIAT in RT-qPCR." (PMID 35383152, 2022).
diabetes (18 papers, 2017 to 2025). "Lnc RNA myocardial infarction associated transcript (MIAT) is also found to inhibit EC proliferation, migration, and tube formation in diabetes via the sponging of miR-29b." (PMID 34026872, 2021). "Clinical investigations in diabetes patients had shown that increased expression of MIAT was markedly associated with diabetic retinopathy process, and the increased MIAT decreased the viability of ARPE-19 cells in vitro via targeting the TGF-β1 pathway." (PMID 32190702, 2020). "The observation that overexpression of MIAT is associated with deterioration of retinal function in diabetes is in sharp contrast with results showing detrimental effects of reduced MIAT levels on cell viability in renal tubules." (PMID 28829354, 2017). "Additionally, the knockdown of MIAT significantly improved retinal microvascular dysfunction caused by diabetes in vivo and suppressed endothelial cell proliferation, migration, and tube formation in vitro." (PMID 39773033, 2025). "MIAT was confirmed to be implicated in the regulation of vascular function, including corneal angiogenesis, retinal angiogenesis and vascular leakage, and was also identified as a regulator of retinal neurodegeneration in diabetes." (PMID 37762249, 2023). "Lnc MIAT: Lnc-RNA myocardial-infarction-associated transcript (MIAT), also known as retinal non-coding RNA 2 (RNCR2), has been associated with cell proliferation, apoptosis and migration in many diseases, such as myocardial infarction, microvascular dysfunction and diabetes." (PMID 37762249, 2023). "For example, the expression of MIAT, a long noncoding RNA (lncRNA), increased in diabetic retinas, while MIAT knockdown ameliorated diabetes mellitus-induced retinal microvascular dysfunction." (PMID 35346383, 2022). "MIAT regulates diabetes-induced microvascular dysfunction by competing with endogenous vascular endothelial growth factor and miR-150 in retinal endothelial cells." (PMID 36620092, 2022). "Taken together, our study showed that the expression of MIAT is significantly decreased in the diabetic retina after the injection of HUMSCs." (PMID 32210708, 2020). "The expression of myocardial infarction-associated transcript (MIAT) is significantly elevated in diabetic rats and patients, and MIAT knockout reduces the release of proinflammatory cytokines induced by diabetes." (PMID 32295041, 2020). "Like MALAT1, MIAT is also upregulated in the retinas and peripheral blood mononuclear cells of diabetes patients, and is furthermore upregulated in peripheral blood leukocytes of ischemic stroke patients." (PMID 30893946, 2019). "They found decreased expression of both MIAT and Nrf2 in diabetes-induced renal tubule, as well as in HG exposed HK-2 cells, which inversely correlated with serum creatinine and BUN." (PMID 29915562, 2018). "The mechanism by which MIAT affects renal tubule function within the context of diabetes remains to be determined; exploration of the MIAT-miR-150-5p relationship in renal tubule cells is also likely to shed light on these differences." (PMID 28829354, 2017). "Studies have shown that MIAT knockdown could alleviate diabetes-induced inflammation responses and vascular leakage." (PMID 32210708, 2020). "Researchers showed that the abnormal expression of MIAT was involved in the cell proliferation, apoptosis and migration in many diseases, such as myocardial infarction, microvascular dysfunction and diabetes." (PMID 28246353, 2017). "MIAT knockdown can't only reverse the inflammation-induced negative effects to promote osteogenesis of human adipose-derived stem cells 26, but also inhibit the upregulation of diabetes mellitus-induced proinflammatory factors to alleviate retinal inflammation." (PMID 32210708, 2020). "In addition, MIAT is found to be increased in a mouse diabetes model and in vitro after high glucose treatment, which is at least partially the effect of increased binding of the protein complex NF-κB to the MIAT promotor." (PMID 30893946, 2019).
atherosclerosis (17 papers, 2017 to 2025). A disease characterized by the build-up of fatty material and calcium deposition in the arterial wall resulting in partial or complete occlusion of the arterial lumen. "The level of some lncRNAs, such as CASC11, H19, TUG1, and MIAT, can be analysed in serum samples as potential diagnostic markers for atherosclerosis." (PMID 39273193, 2024). "When further examining microRNA pathways in atherosclerosis, studies have identified the lncRNA myocardial-infarction-associated transcript (MIAT) in macrophages as a key player." (PMID 35884884, 2022). "For instance, the lentiviral shRNA targeting of lncRNA myocardial infarction associated transcript (MIAT) significantly attenuates atherosclerosis progression and increases plaque stability in vivo." (PMID 34421622, 2021). "In turn, MIAT silencing hampered the progression of atherosclerosis in a mouse model of advanced atherosclerosis." (PMID 39273193, 2024). "Moreover, another study demonstrated that MIAT expression was significantly correlated with a variety of indicators of macrophage activity, inflammatory cytokines, and growth factors, as well as vascular smooth muscle cell marker genes, a hallmark of atherosclerosis." (PMID 35884884, 2022). "MIAT also participated in the phenotypical switch of SMC to inflammatory macrophage-like cells that contributes to the progression of atherosclerosis and vascular inflammation." (PMID 35884884, 2022). "Further, MIAT was upregulated in rats with atherosclerosis, and it aggravated the atherosclerotic damage through PI3K/Akt activation." (PMID 35784351, 2022). "Silencing of MIAT attenuated atherosclerosis progression in an advanced atherosclerosis mouse model." (PMID 34179148, 2021). "Subsequent knockdown of MIAT in vivo demonstrated that silencing of MIAT significantly enhanced phagocytic clearance and reduced atherosclerosis plaque progression and instability." (PMID 30755588, 2019). "MIAT knockdown attenuated atherosclerosis progression, reduced necrotic core size, and increased plaque stability in vivo." (PMID 30755588, 2019). "To study the function of MIAT and examine the therapeutic potential in atherosclerosis, we knocked-down MIAT in vivo using systemically delivered viral MIAT shRNA in ApoE−/− mice." (PMID 30755588, 2019). "Recent studies have reported that lncRNA MIAT has critical functions in many cancers and microvascular dysfunction, but little is known about its roles in the progression and instability of atherosclerosis." (PMID 30755588, 2019). "LncRNAs, including H19, TUG1, MIAT, and CASC11, can be detected in serum and could serve as potential diagnostic markers for atherosclerosis." (PMID 40941416, 2025). "MIAT expression is elevated in the macrophages found in the necrotic core of atherosclerotic mouse models, as well as in the serum from patients with advanced atherosclerosis." (PMID 35884884, 2022). "Additionally, MIAT stimulates cellular proliferation through the miR-181b/STAT3 signaling pathway in an atherosclerosis cell model." (PMID 35053285, 2022). "In the current study, we found that MIAT was significantly upregulated in serum of patients with symptoms of atherosclerotic vulnerable plaque and was consistently increased in serum and macrophages of necrotic cores in an advanced atherosclerosis mouse model." (PMID 30755588, 2019). "During the process of angiogenesis, which is anatural phenomenon after a CAD event, MIAT could significantly beup-regulated, subsequently sponging miR-150-5p, thereby up-regulating the level ofVEGF and other factors contributing to atherosclerosis." (PMID 31188931, 2019). "Furthermore, we determined that systemically delivered viral MIAT shRNA significantly reduced atherosclerosis progression in vivo and promoted plaque stability by enhancing the clearance of apoptotic cells by lesion macrophages in ApoE−/− mice." (PMID 30755588, 2019).
atherosclerosis (continued). "In addition,MIAT was shown to be involved in vascular endothelialdysfunction, which suggests a role in the pathogenesis of atherosclerosis." (PMID 31188931, 2019). "The modulation of MIAT may provide an intriguing approach for prevention of atherosclerosis and tackling its treatment." (PMID 30755588, 2019). "Deregulation of lncRNAs, including H19, TUG1, GAS5, RAPIA, MIAT, CASC11, NEXN-AS1, and lnc00113, has been observed in individuals with atherosclerosis." (PMID 40941416, 2025). "The deregulation of many lncRNAs, including RAPIA, H19, CASC11, GAS5, TUG1, MIAT, lnc00113, and NEXN-AS1, has been observed in patients with atherosclerosis." (PMID 39273193, 2024). "MIAT activation was also demonstrated to enhance angiogenesis and increase the expression of inflammatory factors (IL-1β, IL-6, and TNF-α) in mice with atherosclerosis." (PMID 39273193, 2024). "In the current study, we first found that MIAT expression levels in the serum were elevated in symptomatic patients with vulnerable plaques and HFD-fed ApoE−/− mice with advanced atherosclerosis." (PMID 30755588, 2019). "Therefore, our study provides new insights into the molecular function of the MIAT/miR-149-5p/CD47 signaling pathway in the pathogenesis of plaque vulnerability and highlights the potential of MIAT as a new therapeutic target for atherosclerosis." (PMID 30755588, 2019).